NOTCH3 (notch receptor 3)
Diseases named in the same sentence as NOTCH3 in open-access papers (continued):
Sharing a sentence is not in itself a finding about the gene and the disease.
cerebral microbleeds (8 papers, 2015 to 2025). Cerebral microbleeds are a group of pathological processes affecting the small arteries, arterioles, capillaries and venules of the brain, as detected by brain imaging techniques. "NOTCH3 variants were associated with an increased risk of the presence of lacunes (OR: 5.97, 95% CI: 2.00 to 12.06, p=0.0002) and cerebral microbleeds (OR: 4.38, 95% CI: 1.69 to 7.76, p=0.0003)." (PMID 33712516, 2021). "In contrast, the lacunes and cerebral microbleeds in patients with NOTCH3 cysteine-sparing mutations were more severe than those in typical CADASIL (74.29% vs. 62.00%, 72.73% vs. 35.80%, respectively), particularly for cerebral microbleeds with a significantly statistically higher proportion." (PMID 39201482, 2024). "NOTCH3(+) svMCI group had much greater increases in the lacune and cerebral microbleed counts than the NOTCH3(–) svMCI group." (PMID 33716917, 2021). "Comparison of longitudinal changes in the number of lacunes and cerebral microbleeds in patients with subcortical vascular mild cognitive impairment (svMCI), with and without NOTCH3 variant." (PMID 33716917, 2021).
cognitive decline (8 papers, 2013 to 2024). "The finding suggests that a disturbed neurogenic process due to Notch3-dependent micromilieu changes might be one vascular-independent mechanism contributing to cognitive decline observed in CADASIL." (PMID 28345617, 2017). "Structural alterations in the small penetrating cerebral and leptomeningeal arteries in CADASIL caused by pathogenic mutations in NOTCH3 (Notch homolog 3) lead to NVU impairment, causing cerebral blood flow reduction and subcortical ischemia, with lacunar infarcts correlating with cognitive decline." (PMID 28042305, 2016). "The study will be completed across five centres in three states in Australia with an anticipated 150 NOTCH3 positive individuals (confirmed CADASIL, suspected CADASIL-either NOTCH3 positive or symptomatic) and equivalent NOTCH3 negative healthy controls without cognitive decline." (PMID 38226362, 2024).
Obesity (8 papers, 2016 to 2024). Accumulation of substantial excess body fat. "This study found that miR-204-5p inhibited adipocyte differentiation by acting on the AMPK signaling pathway and the JAG1/NOTCH3 axis, suggesting potential targets for the treatment of obesity and other related metabolic diseases." (PMID 38388551, 2024). "In addition, we demonstrate that NOTCH3 is enriched in the premyofibroblast progenitor subset, which preferentially accumulates in the visceral AT of patients with an early obesity trajectory." (PMID 36617688, 2023). "Progenitor NOTCH3 may constitute a tool to monitor replicative senescence and to limit AT dysfunction in obesity and aging." (PMID 36617688, 2023). "In general, despite only a few previous evidences support an implication of the Notch3 gene in obesity molecular pathways, the findings presented in this paper seem to point this TF as an important element for the proper regulation of AT cellular responses to WL." (PMID 32275707, 2020). "Additionally, a direct correlation between BMI and gene expression was observed for AGER, ANGPT2, CD68, IFI30, NOTCH3 and SPP1, whereas an inverse correlation was achieved for DLL4, PLIN, PNPLA2 and VEGF (genes that were down-regulated due to obesity)." (PMID 33022994, 2020). "Although no target sites for Notch3 have been identified within the genetic sequence of Egfl6, a special functional connection has been evidenced between both genes in the context of obesity and angiogenesis." (PMID 32275707, 2020). "Altogether, our study revealed that Notch3 promotes adipocytic differentiation of 3T3‐L1 pre‐adipocytes cells by up‐regulating LARS expression and activating the mTOR pathway, which might be an emerging target for obesity treatment." (PMID 31755192, 2020).
squamous cell carcinoma (8 papers, 2013 to 2025). A carcinoma arising from squamous epithelial cells. "Positive Notch3 expression was identified in the cytoplasm and nuclei in the squamous cell carcinoma and adenocarcinoma groups, and the adenocarcinoma groups demonstrated a stronger positive expression." (PMID 23420695, 2013). "In this manuscript, the authors reveal that Notch1 activation and EMT promote tumor initiation and cancer cell heterogeneity in squamous cell carcinoma, while the repression of Notch3 by ZEB1 limits Notch1-induced differentiation, permitting Notch1-mediated EMT." (PMID 29170450, 2017). "Although the function of Notch3 is highly indicated to squamous cell differentiation, studies of Notch1function in response to hypoxia in squamous cell carcinoma cell lines and large series of clinicopathological correlation of Notch1 in human squamous cell carcinomas are still missing." (PMID 23409141, 2013). "In all the studied samples (11 adenocarcinoma (ADC) and 10 squamous cell carcinoma (SCC)), the expression of Notch3 was very strong in the vasculature." (PMID 28719575, 2017). "Indeed, in squamous cell carcinoma, NOTCH1 induces the expression of Zinc finger E-box-binding homeobox 1 (ZEB1), a transcription factor that acts as a negative regulator of Notch3 gene expression." (PMID 32908186, 2020). "Notch3 expression in the cancer tissue was stronger than that of the corresponding non-tumor tissue in the squamous cell carcinoma and adenocarcinoma groups; the difference was statistically significant (P<0.01)." (PMID 23420695, 2013).
adenoma (7 papers, 2013 to 2020). A neoplasm arising from the epithelium. "Quantitation of percentage of NOTCH3 positive cells per total cells showed higher levels in corticotropinomas and somatotropinomas compared to non functioning adenomas." (PMID 28915655, 2017). "Higher NOTCH3 staining detected in corticotropinomas suggest a more active Notch pathway in this adenoma subtype in accordance with results obtained in ATt20 cells compared to prolactinoma cell lines." (PMID 28915655, 2017). "The expression level of Dll1, Dll3, Jagged1, Jagged2, Notch3, and Hes5 was similar in the small intestine adenomas and the normal tissue epithelium." (PMID 28086833, 2017). "The same Notch members and Hes1, instead of Hes5, seemed upregulated in the adenomas (Notch3 only in the large intestine)." (PMID 28086833, 2017). "Remarkably, positive correlations between the expression of NOTCH1-2,4 and the HES1 target gene, and between NOTCH3 with the ligand JAGGED1 were found in the cohort of samples used when all adenomas were considered, independently of tumor histotype." (PMID 28915655, 2017). "GeneChip microarrays and proteomics analyses demonstrated increased expression of NOTCH3 in non functioning and prolactin secreting adenomas in humans while in somatotropinomas a significantly reduced expression of NOTCH3 was found." (PMID 28915655, 2017). "KrasG12D upregulates expressions of Notch2, Notch3, Notch4, Jag1 and downstream target genes Hes1, Hey1 and Hey2, and deletion of Jag1 partially suppresses KrasG12D-induced adenoma development." (PMID 29142904, 2017). "Our data demonstrated paralleled expression of Notch3 between PRL-secreting adenomas and normal controls." (PMID 23426998, 2013). "The expression of Notch3 was moderately elevated in NFPAs compared with functional adenomas, which included GH- and PRL-secreting adenomas." (PMID 23426998, 2013). "In contrast to its receptor (Notch3), Jagged1 mRNA expression levels in GH-secreting adenomas were similar to normal (P= 0.881)." (PMID 23426998, 2013). "GH-secreting adenomas (n=5) demonstrated significantly reduced expression (∼75% reduction) of Notch3 compared with normal tissue (P=0.036)." (PMID 23426998, 2013). "GeneChip microarrays and proteomic analyses have demonstrated an increased expression of Notch3 in PRL-secreting adenomas." (PMID 23426998, 2013). "In prolactinomas and non functioning adenomas NOTCH3 cells were scattered and isolated." (PMID 28915655, 2017). "Importantly, NOTCH3 positive cells were higher in corticotropinomas and somatotropinomas compared to non functioning adenomas." (PMID 28915655, 2017). "In accordance with Notch3 involvement in pituitary tumorigenesis, we found NOTCH3 immunopositive cells in every human adenoma sample tested with higher levels in corticotropinomas and somatotropinomas, and a remarkable disposition of positive cells in clusters in these two adenoma types." (PMID 28915655, 2017). "Notch3 protein expression levels of GH- and PRL-secreting adenomas were similar to those of normal pituitary tissue (n=5, P>0.05; n=4, P>0.05, respectively)." (PMID 23426998, 2013). "Comparatively, in adenomas, ≥2-fold Notch3 expression was detected in 56% followed by Notch1 (44%), Notch4 (33%), and Notch2 (11%), while for ligand Jag1, mRNA was overexpressed in 33%, Jag2, Dll1, and Dll3 in 11%, whereas Dll4 was not expressed in adenomas." (PMID 32211044, 2020). "Unlike RT-PCR analysis, Notch3 protein expression was significantly elevated in NFPAs compared with functioning adenomas (n=9, with 5 GH-secreting adenomas and 4 PRL-secreting adenomas; P=0.002)." (PMID 23426998, 2013). "Using quantitative real-time RT-PCR assays and western blot analyses, upregulated Notch3 and Jagged1 were observed in human NFPAs, but not in normal human pituitary glands or in hormone-secreting adenomas." (PMID 23426998, 2013).
adenoma (continued). "In the current study, we have provided evidence of Notch3 expression in human functioning adenomas, a finding that has not been previously reported." (PMID 23426998, 2013). "Additionally, nonfunctioning adenomas demonstrated increased expression of Notch3 compared with functioning adenomas, which included PRL- and GH-secreting adenomas (P=0.026)." (PMID 23426998, 2013). "Up-regulated Notch3 and JAG1 have been observed in human non-functional PAs, but not in human pituitary glands or hormone-secreting adenomas." (PMID 33425722, 2020). "Previous studies have demonstrated that Dll1, a potential ligand of Notch3, was strongly downregulated in non-functional tumors and in PRL-secreting adenomas." (PMID 23426998, 2013). "In the majority of examined PA samples, an increase has been found in the expression of relative Notch3 and JAG1 mRNA, which may be a crucial factor in the initiation and proliferation of human non-functional adenomas." (PMID 33425722, 2020).
arteriopathy (7 papers, 2018 to 2022). "Lacunes in CADASIL are caused by reduced microvascular perfusion due to small arteriopathy affected by NOTCH3 mutation." (PMID 33716917, 2021). "NOTCH3 mutations cause arteriopathy affecting the small cerebral (deep) and leptomeningeal (superficial) penetrating arteries, and CMBs might result from vascular leakage of these fragile small vessels." (PMID 33716917, 2021). "Altered Notch3 signaling has been proved in variant outside EGFr region, for example, variant L1515P, suggesting that variant outside EGFr might lead to arteriopathy by dysregulating Notch3 signaling." (PMID 34335700, 2021).
atherosclerosis (7 papers, 2016 to 2025). A disease characterized by the build-up of fatty material and calcium deposition in the arterial wall resulting in partial or complete occlusion of the arterial lumen. "The mechanism by which NOTCH3 mutations cause atherosclerosis in large arteries has been less well studied." (PMID 41018180, 2025). "Clonal analysis further showed that NOTCH3+ fcVSMCs derive from intermediate VSMCs in both atherosclerosis and an acute vascular injury model, suggesting a conserved disease-relevant mechanism." (PMID 40577585, 2025). "Notch3 expression was largely confined to fcVSMCs in both atherosclerosis and injury, whereas Vcam1 was highly expressed by imVSMCs and down-regulated in fcVSMCs." (PMID 40577585, 2025). "Additionally, a cell population co-expressing contractile genes with key ECM genes (Col1a1, Mgp, Eln, Fn1, Col4a1, and Col8a1) and Notch3, mapped together with the fcVSMC population from the atherosclerosis dataset (I-cluster 6)." (PMID 40577585, 2025). "Thus, Notch3 was used as a marker of endothelial to mesenchymal transition during atherosclerosis, and in hepatic stellate cell activation and transdifferentiation to myofibroblasts." (PMID 35611804, 2022). "In macrophages isolated from patients with atherosclerosis, NOTCH1 appears to play a more prominent role than those of NOTCH2 and NOTCH3 in the regulation of the NF-κB signaling pathway and in the induction of pro-inflammatory gene expression." (PMID 35891967, 2022).
CARASIL (7 papers, 2013 to 2023). CARASIL is a hereditary cerebral small vessel disease characterized by early-onset gait disturbances, premature scalp alopecia, ischemic stroke, acute mid to lower back pain and progressive cognitive disturbances leading to severe dementia. "A number of different genes come under the umbrella term of vascular leukoencephalopathies, including NOTCH3 (CADASIL), HTRA1 (cerebral autosomal recessive arteriopathy with subcortical infarcts and leukoencephalopathy (CARASIL)), CTSA (CARASAL), COL4A1 and TREX1." (PMID 30467211, 2019).
esophageal cancer (7 papers, 2017 to 2025). A primary or metastatic malignant neoplasm involving the esophagus. "NOTCH3 is another important regulator associated with chemotherapy resistance in esophageal cancer cells when downregulated." (PMID 37239838, 2023). "For example, NAT10 enhances the metastasis of esophageal cancer by stabilizing NOTCH3 mRNA via ac4C modification." (PMID 40999468, 2025). "In this study of esophageal cancer, silencing NOTCH3 resulted in increased production of VIM and resulted in increased chemotherapy resistance." (PMID 37239838, 2023).
Multiple Myeloma (7 papers, 2013 to 2026). "Myeloma cells increase NOTCH3 in osteocytes, and genetic activation of NOTCH3 in osteocytes leads to bone loss." (PMID 37174109, 2023). "Mechanistic studies revealed that osteocyte proliferative signals are mediated by NOTCH3 in myeloma cells." (PMID 37174109, 2023). "In an in vivo model of multiple myeloma, inhibition of NOTCH3 signaling in myeloma cells, which is the receptor mediating osteocyte–myeloma communication, resulted in a reduction in tumor size." (PMID 37174109, 2023). "Consistent with this, injection of NOTCH3 knockdown myeloma cells into mice resulted in fewer lytic lesions." (PMID 37174109, 2023). "Genetic knockdown of NOTCH3 in myeloma cells prevented the increase in CYCLIN D1 expression and proliferation induced by osteocytes." (PMID 37174109, 2023). "Inhibition of NOTCH3 in myeloma cells reduced osteocyte-induced RANKL upregulation." (PMID 37174109, 2023). "However, in this study, NOTCH3 knockdown in myeloma cells suppressed tumor burden." (PMID 37174109, 2023).
neuroblastoma (7 papers, 2009 to 2021). Neuroblastoma (NB) is the most common solid, extracranial childhood tumor. "Our Wnt DEGs also showed a correlation with the NOTCH3-ICD regulated transcriptome in neuroblastoma, but to a lesser extent than BMP4." (PMID 32210188, 2020). "In two additional ADRN neuroblastoma cell lines, we confirmed that NOTCH3-IC induced a MES marker profile and a migratory phenotype." (PMID 30948783, 2019). "Here we identified MSX2 mediated activation of the NOTCH3-pathway in T-cells reminiscent of MSX1 in neuroblastoma." (PMID 19835636, 2009). "Notch pathway targets and effectors were highly induced in our RNA-seq of IMR32 treated with BMP4, so we first validated a panel of Notch pathway genes, including HES1, MAFB, MAML2 and NOTCH3, confirming a BMP4-Notch signaling pathway in neuroblastoma." (PMID 32210188, 2020). "RT-qPCR analysis of the three mammalian Notch receptors (Notch 1, Notch 2, and Notch 3) in SH-SY5Y, KELLY and IMR-32 neuroblastoma cell lines." (PMID 28525978, 2017). "The association of CXCR4 expression to site-specific metastasis, into BM of neuroblastoma-bearing patients, and the supportive effect of endothelial niche in Notch-dependent T-ALL cells maintenance, favor our hypothesis that Notch3/CXCR4 crosstalk directs “pre-leukemic” DP-cells to the BM." (PMID 30038265, 2018).
ovarian tumor (7 papers, 2014 to 2021). "Changes in cell adhesion and migration can profoundly affect metastasis, and a previous in vitro study suggested that Notch3 increases adhesion between ovarian tumor cells and co-cultured mesothelial cells." (PMID 32525899, 2020). "Ovarian tumors frequently show high levels of Notch3 signaling, particularly in HGSC cases and HGSC-derived cell lines." (PMID 32525899, 2020). "Various studies have detected Notch1 and Notch3 expression in ovarian tumors by IHC, real-time polymerase chain reaction, and/or immunoblotting." (PMID 25072022, 2014). "Notch3 high protein expression was detected in high-grade ovarian tumors." (PMID 28415574, 2017). "It is also possible that there is synergism between Notch3-mediated and Notch3-independent changes in adhesion, in particular upregulation of COL11A1, which is unaltered by Notch3 signaling but associated with poor survival in human HGSC and ovarian tumor progression in mouse models." (PMID 32525899, 2020).
serous ovarian cancer (7 papers, 2014 to 2021). "Patients with high grade serous ovarian adenocarcinomas showing high Notch3 expression have a significantly worse clinical outcome, including reduced overall survival and shortened progression-free survival than patients with low Notch3 expression." (PMID 31182109, 2019). "Ectopic expression of Notch3 following transduction with a Notch3 intracellular domain (NICD3) in ovarian surface epithelium and low-grade serous ovarian cancer cell lines with low endogenous Notch3 expression led to increased resistance to carboplatin in vitro." (PMID 25366565, 2014).
Arthritis (6 papers, 2021 to 2025). Inflammation of a joint. "In a mouse model of antibody-mediated arthritis induced by transfer of K/BxN mouse serum, Notch3-deficient mice were resistant to arthritis induction and anti-Notch3 neutralizing antibodies blunted disease severity (with lesser effects for anti-Notch1 antibodies)." (PMID 34124039, 2021). "One subtype of note is a population of NOTCH3+ (neurogenic locus notch homolog protein 3) fibroblasts that has been shown to proliferate in the sub-lining of joint synovial membrane in arthritis." (PMID 40381746, 2025). "Inhibition of NOTCH3 signaling by antibody or gene knockout of Notch3 suppressed inflammation and bone destruction in the mouse model of serum transfer-induced arthritis." (PMID 36982247, 2023). "NOTCH3 gene deleted mice develop a normal joint structure suggests that NOTCH3 targeted therapy is safe for treating arthritis." (PMID 35252279, 2022). "In a rat CIA model, a NOTCH1 and NOTCH3 inhibitor (LY411575) showed therapeutic effect of arthritis, presumably by inducing fibroblast death since LY411575 is able to induce death of human synovium derived fibroblast cell line, MH7A in vitro." (PMID 35252279, 2022). "The genetic deletion of Notch3 or antibody mediated therapeutic blockade of NOTCH3 signaling led to attenuated arthritis." (PMID 34539648, 2021). "Furthermore, NOTCH3 knockout mice had diminished arthritis induced by KBxN serum transfer compared with wild type animals." (PMID 35252279, 2022). "Genetic deletion or blockade of Notch3 signaling has been shown to inhibit THY1+ sub-lining perivascular fibroblast expansion in mice and importantly attenuate experimental arthritis." (PMID 34539648, 2021).